HLA-DRB1 (major histocompatibility complex, class II, DR beta 1)
Diseases named in the same sentence as HLA-DRB1 in open-access papers (continued):
Sharing a sentence is not in itself a finding about the gene and the disease.
rheumatoid arthritis (continued). "More, in a studied population, rheumatoid nodule frequency correlates directly with the prevalence of HLA-DRB1*04:01 of this population." (PMID 34248985, 2021). "HLA-DRB1 shared epitope (SE) alleles are important genetic contributors for the risk of developing anti-citrullinated protein antibodies (ACPA)-positive rheumatoid arthritis (RA), particularly in Caucasians." (PMID 33327594, 2020). "Rheumatoid arthritis is a chronic inflammatory disease that affects the joints.Almost all RA patients carry the HLA-DRB1*0401,HLA-DRB1*0404, HLA-DRB1*0405 orHLA-DRB1*0101 allele." (PMID 31993230, 2019). "Three of the 11 independent amino acid variations, HLA-DRB1 residue 67 and 71, HLA-DQB1 residue 55 are associated with type 1 diabetes, multiple sclerosis, hypothyroidism, rheumatoid arthritis, and inflammatory polyarthritis according to PheWAS database." (PMID 31543879, 2019). "Rheumatoid Arthritis (RA) pathogenesis is a multistep process between the dysregulated neuro-immune system, abnormal neuro-endocrine-immune and the individual’s genetic background (for example the HLA-DRB1 gene) that may predispose some people to excessive cytokine responses." (PMID 29401671, 2018). "The level of expression of HLA-DRB1 alleles have been associated with the development of systemic lupus erythematosus (SLE), rheumatoid arthritis (RA), systemic sclerosis (SSc) and multiple sclerosis (MS)." (PMID 27713139, 2017). "The aetiological association between genes and environmental factors in the development of rheumatoid arthritis (RA) is well-established today, with specific HLA-DRB1 alleles, termed the shared epitope (SE), as the major genetic contributor, and smoking as the main environmental risk factor." (PMID 28962582, 2017). "The genetic association of HLA-DRB1 with rheumatoid arthritis (RA) and systemic lupus erythematosus (SLE) is well documented, but association with other HLA-DR beta genes (HLA-DRB3, HLA-DRB4 and HLA-DRB5) has not been thoroughly studied, despite their similar functions and chromosomal positions." (PMID 26919467, 2016). "HLA-DRB1*0401 is associated with susceptibility, while HLA-DRB1*0402 is associated with resistance to developing rheumatoid arthritis (RA) and collagen-induced arthritis in humans and transgenic mice respectively." (PMID 22553482, 2012). "The HLA-DRB1 gene has long been known to be a major rheumatoid arthritis (RA) susceptibility locus." (PMID 20018090, 2009). "The genes PTPN22 and HLA-DRB1 have been found by a number of studies to confer an increased risk for rheumatoid arthritis (RA), which indicates that both genes play an important role in RA etiology." (PMID 20017999, 2009). "There is another locus on chromosome 6 about 5 cM away from the HLA-DRB1 locus that contributes to the development of rheumatoid arthritis (RA)." (PMID 18466479, 2007). "The vast majority of patients with rheumatoid arthritis (RA) carry human leukocyte antigen-DRB1 (HLA-DRB1) alleles encoding QKRAA, QRRAA, or RRRAA amino acid sequences in positions 70 to 74 of the DR-β chain, a motif commonly known as the RA 'shared epitope' (SE)." (PMID 17254342, 2007). "HLA-DRB1*14 also is strongly associated with IgG4-AID in our study, and was also reported as increased in patients with rheumatoid arthritis, Guillain-Barré syndrome and MuSK MG22, suggesting it may be a genetic risk factor to develop autoimmune diseases." (PMID 35654912, 2022). "Immune complexes containing anti-α501-515cit antibodies and rheumatoid factors might be involved in the development of rheumatoid nodules on the HLA-DRB1*04:01 background." (PMID 34248985, 2021). "Based on previous studies, various HLA-A and HLA-DRB1 alleles have been shown to be associated with increased susceptibility to multiple autoimmune diseases, such as anti-LGI1 encephalitis, multiple sclerosis (MS), and rheumatoid arthritis (RA)." (PMID 33160385, 2020).
rheumatoid arthritis (continued). "Furthermore, Leu74 of HLA-DRB1 was identified in Japanese patients with GD and rheumatoid arthritis." (PMID 31091281, 2019). "We also identified two specific intronic variations in HLA-DRB1 that might be involved in rheumatoid arthritis." (PMID 30337930, 2018). "HLA-DRB1 was reported to have participated in the pathopoiesis of rheumatoid arthritis." (PMID 28835756, 2017). "HLA-DRB1 and CD2AP gene were identified to be among the susceptibility genes of KBD, thus supporting the role of the autoimmune response in KBD and the possibility of shared etiology between osteoarthritis, rheumatoid arthritis, and KBD." (PMID 24776925, 2014). "LEF treated active rheumatoid arthritis patients with the HLA-DRB1 gene." (PMID 23369524, 2013). "This SNP was also associated in a recent GWAS of rheumatoid arthritis, but its independence from the known HLA-DRB1 effect was not described." (PMID 23991122, 2013). "The number of copies of the HLA-DRB1 shared epitope, and the minor alleles of the STAT4 rs7574865 and the PTPN22 rs2476601 polymorphisms have all been linked with an increased risk of developing rheumatoid arthritis." (PMID 22937072, 2012). "HLA-DRB1*0405 was significantly associated with susceptibility to rheumatoid arthritis in Malays and Chinese, but not in Indians." (PMID 21698259, 2011). "Non-inherited maternal antigens encoded by specific HLA-DRB1 alleles (NIMA) have been implicated as a rheumatoid arthritis (RA) risk factor." (PMID 18466466, 2007). "Polymorphism in the HLA-I (HLA-A, B, and C) and HLA-II (HLA-DRB1, DQB1, DQA1, DPB1, and DPA1) loci is a hallmark of genetic risk for autoimmune diseases; for example, genetic variation in the HLA-II loci explains up to 30% of the genetic heritability in rheumatoid arthritis and type 1 diabetes." (PMID 39085222, 2024). "In the case of rheumatoid arthritis (RA), the HLA-DRB1, HLA-A, HLA-B, and HLA-DPB1 genes constitute genetic susceptibility for the development of the disease." (PMID 36981837, 2023). "The HLA-DRB1*07:01 allele has been linked as a risk factor for systemic lupus erythematosus (SLE) in the Malaysian population, whereas in the Chilean population, HLA-DRB1*07:01 had a protective role in anti-citrullinated protein antibodies-positive rheumatoid arthritis." (PMID 35335034, 2022). "For example, human susceptibility to rheumatoid arthritis (RA) was found linked strongly with certain MHC class I and II alleles, including HLA-DRB1, HLA-DPB1 and HLA-B." (PMID 31720104, 2019). "As an example of future HLA-related disease and transplantation studies, we identified specific variations and previously “undetermined” sequence regions in the HLA-DRB1 locus of these Japanese reference samples that might be related to rheumatoid arthritis (RA)." (PMID 30337930, 2018). "Many studies have reported that both a ‘shared epitope’ (SE) encoded by several HLA-DRB1 alleles and the peptidyl arginine deiminase type 4 (PADI4) gene polymorphisms are associated with susceptibility to rheumatoid arthritis (RA)." (PMID 28182665, 2017). "Similarly, peptides from DnaJ of microbial protein may bind human HLA-DRB1*04:01 molecules and may be involved in the development of rheumatoid arthritis (RA)." (PMID 29062305, 2017). "Thus, HLA-DRB1 SE/RF-positive patients with the AA genotype of rs1805010 and the AA or AG genotype of rs1801275 have a higher risk of rheumatoid nodules than do those patients without this feature." (PMID 20444266, 2010). "However, HLA-DRB1 SE status alone does not appear to increase significantly the risk of rheumatoid nodules among African Americans." (PMID 20444266, 2010). "The DRB1*04 allele of the human leukocyte antigen (HLA) system is a known risk factor for the development of rheumatoid arthritis (RA) and is associated with increased serum levels of antibodies against cyclic citrullinated antibodies (anti-CCP) together with HLA-DRB1 *01 and HLA-DRB1*10 alleles." (PMID 41325321, 2025).
rheumatoid arthritis (continued). "Haplotypes defined by amino acids at HLA-DRB1 positions 11, 71 and 74 associated with susceptibility to rheumatoid arthritis (RA) are associated with radiological outcome, anti-TNF response and all cause-mortality in RA." (PMID 35468805, 2022). "In the context of autoimmune disease-related ILDs, the HLA-DRB1*14:06, *15, and *16 alleles are associated with a higher risk of developing an ILD in patients with rheumatoid arthritis (RA) in Asian populations, while the HLA-DRB1*04 allele is associated with a reduced risk for ILD." (PMID 36359012, 2022). "We used MEDLINE for our literature search of the following terms: rheumatoid arthritis/RA, cigarette smoking, anti-citrullinated cyclic peptide/protein antibody/ACPA, rheumatoid factor/RF, HLA-DRB1, shared epitope allele, environmental risks, genetic risks, and single nucleotide polymorphisms/SNPs." (PMID 32092988, 2020). "Assessment of interaction between HLA-DRB1 shared epitope (SE) (positive or negative) and smoking (ever or never) in rheumatoid arthritis (RA) risk in Chinese Han population." (PMID 28674691, 2017). "In rheumatoid arthritis (RA) and small-vessel vasculitis, genetically distinct subsets have been identified that have different associations with the major histocompatibility complex (MHC) region that encodes the HLA-DRB1 alleles." (PMID 26223536, 2015). "Assessment of interaction between HLA-DRB1 shared epitope (SE) (positive or negative) and cumulative smoking exposure (≥10 pack-years, <10 pack-years, or never smoking) in rheumatoid arthritis (RA) risk in Chinese Han population." (PMID 28674691, 2017). "As with the original DMG-alone analysis, the MEGs were also significantly 3.75-fold enriched in the KEGG ‘Rheumatoid arthritis‘ pathway (q = 1.70E-02, where q is a multiple-test corrected P-value) with 7 out of 89 genes: ANGPT1, CSF2, CTLA4, HLA-DQA1, HLA-DQA2, HLA-DRA and HLA-DRB1." (PMID 25901943, 2015). "Focusing on chromosome 1, a recursive partitioning linkage algorithm (RP) was applied to perform linkage analysis on the rheumatoid arthritis NARAC data, incorporating covariates such as HLA-DRB1 genotype, age at onset, severity, anti-cyclic citrullinated peptide (anti-CCP), and life time smoking." (PMID 18466580, 2007). "In the present paper, we used the North American Rheumatoid Arthritis Consortium data provided for Genetic Analysis Workshop 15 Problem 2 to: 1) estimate the penetrances of PTPN22 and HLA-DRB1 and, 2) test the selected model of PTPN22 conditional on the rheumatoid factor status." (PMID 18466483, 2007). "Testing genetic models of rheumatoid arthritis that include the PTPN22 SNP in addition to the HLA-DRB1 locus did not affect the results, nor did subgroup analysis of PTPN22 conditional on the rheumatoid factor status." (PMID 18466483, 2007). "A similar difference could be found for HLA-DRB1*04, which is increased in classical AID diabetes mellitus type 1, rheumatoid arthritis and autoimmune hepatitis patients, but decreased in IgG4-AID (MuSK, TTP and CIDP)—with the exception of pemphigus, where a strong association was observed." (PMID 35654912, 2022). "Indeed, 44/155 patients expressed HLA-DRB1*04:01 of whom 11 (25%) had rheumatoid nodules, 111/155 patients did not express HLA-DRB1*04:01 of whom 19 (17%) had rheumatoid nodules (Chi2, OR = 2.15 [0.91 – 5.25]; p = 0.081)." (PMID 34248985, 2021). "Likewise, the majority of individuals who are HLA-B27 positive do not develop spondyloarthritis and the majority of individuals who are HLA-DRB1 positive do not develop rheumatoid arthritis." (PMID 33077849, 2020). "In the patients with type-I diabetes having HLA-DRB1*4 allele associated rheumatoid arthritis, the Type-II collagen antigenicity is increased significantly by oxidative PTMs while its increase is less in type-I diabetes patients without HLA-DRB1*4 allele associated rheumatoid arthritis." (PMID 30258344, 2018).
rheumatoid arthritis (continued). "Established loci for rheumatoid arthritis (RA), including HLA-DRB1 and PTPN22, do not fully account for the genetic component of susceptibility to the disease." (PMID 20017998, 2009). "Until now, HLA-DRB1 genotyping has neither been used in everyday clinical practice, nor included in the current ACR/EULAR 2010 rheumatoid arthritis classification criteria." (PMID 32370106, 2020). "The objective of this study was to examine HLA-DRB1 and HLA-DQB1 genotypes in patients with severe extra-articular rheumatoid arthritis (ExRA) and to compare them with the genotypes of rheumatoid arthritis (RA) patients without extra-articular manifestations." (PMID 16277691, 2005). "Rheumatoid arthritis (RA) affects approximately 0.5 to 1% of the world population and is modulated by immune and inflammatory processes, as well as by class II MHC (in particular the locus HLA-DRB1), non-MHC genes and environmental factors." (PMID 24505471, 2014).
autoimmune disease (116 papers, 2008 to 2025). A disorder resulting from loss of function or tissue destruction of an organ or multiple organs, arising from humoral or cellular immune responses of the individual to their own tissue constituents. "In comparison to other ethnic groups, the HLA-DRB1*07:01 and HLA-DRB1*13:01 alleles in the European and African populations exert a pleiotropic effect on the correlation between susceptibility to autoimmune diseases and pathogen adaptation." (PMID 40300101, 2025). "A common element among these findings is the HLA-DRB1 gene, which is associated with many autoimmune diseases." (PMID 41026325, 2025). "All of these studies highlight the association of HLA-DRB1*04:05 with a predisposition to autoimmune diseases and adverse drug reactions, often with pulmonary involvement, which appears to contrast with our findings." (PMID 40141400, 2025). "While HLA-DRB1 variants have been extensively studied in various autoimmune disorders, this represents one of the first reports associating rs2308760 specifically with GM." (PMID 39796280, 2025). "Both M. tuberculosis and Epstein-Barr virus (EBV) have been implicated in the induction of autoimmune diseases in individuals carrying the HLA-DRB1*15:01-DQB1*06:02 haplotype." (PMID 41425584, 2025). "Extensive research has shown that HLA-DRB1*16:02 is linked to a range of autoimmune disorders, including systemic lupus erythematosus, Graves’ disease, and neuromyelitis optica." (PMID 40693714, 2025). "Molecules of HLA-DRB1 carrying this shared epitope increase the predisposition to RA and other autoimmune diseases." (PMID 39421304, 2024). "HLA-DRB1 is one of the strongest genetic factors for the predisposition to autoimmune diseases; PMR, giant cell arteritis, and RA have similar patterns of HLA association." (PMID 38177227, 2024). "The decrease in the HLA-DRB1*03:01 allele’s frequency in our IgAV patient group is an interesting finding in general since this HLA-DRB1 allele has been identified as a risk factor in numerous autoimmune diseases thus far." (PMID 38255953, 2024). "So far, it has been described that HLA-DRB1*11 alleles and haplotypes are associated with protection against autoimmune diseases and HCV and HBV infections in southern European populations." (PMID 39273401, 2024). "Top ranking MS-associated alleles from our analysis, including HLA-DRB1*03:01, have not only been associated with the development of MS, but also the development of other autoimmune disorders." (PMID 36617594, 2023). "Several autoimmune diseases are associated with HLA-DRB1*03.01 allele, but also with hyper immunoreactivity and rapid progression to the acquired immunodeficiency syndrome in HIV-1 infected patients." (PMID 37492575, 2023). "HLA-DRB1 is a member of the human leukocyte antigen (HLA) gene family and has been linked to the development of autoimmune diseases." (PMID 37569411, 2023). "In particular, HLA class II alleles - and more specifically HLA-DRB1 alleles - are considered to be more strongly involved in the susceptibility to or protection against specific autoimmune diseases than HLA class I." (PMID 36776871, 2023). "Among the HLA-linked genes, many studies have reported that polymorphisms at the HLA-DRB1 locus confer more risk for RA and other autoimmune diseases." (PMID 37746389, 2023). "As for many autoimmune diseases, the effect size for risk of seropositive RA is dominated by several HLA-DRB1 alleles." (PMID 35088123, 2022). "Polymorphisms in the human leukocyte antigen (HLA) gene locus, particularly in HLA-DRB1, are known genetic susceptibility factors for autoimmune diseases." (PMID 35654912, 2022). "Here we demonstrate differential macrophage activation by HLA-DRB1 alleles known to associate with autoimmune disease risk or protection with resultant polarization of pro-inflammatory (“M1”) versus anti-inflammatory (“M2”) macrophages, respectively." (PMID 33510427, 2021).